FAP (fibroblast activation protein alpha)
Diseases named in the same sentence as FAP in open-access papers (continued):
Sharing a sentence is not in itself a finding about the gene and the disease.
tumor (continued). "After the synthesis, the fluorescence of near-infrared fluorescent dyes in the aqueous solution within the liposomes was quenched, and Only FAP-expressing cells were able to take up and activate fluorescence, which improves the diagnostic accuracy of the tumor." (PMID 34490078, 2021). "Therefore, FAP-TAc allows the activation of T-cells and decreases the tumor-associated fibroblasts in tumor stroma." (PMID 33802281, 2021). "Tumor-associated fibroblasts overexpress fibroblast activation protein α (FAPα; seprase)." (PMID 34769123, 2021). "We evaluated whether FAP expression in cancer and stromal cells as determined by immunohistochemistry is associated with tumour progression in patients with newly diagnosed GBM." (PMID 34282761, 2021). "Combination of viral oncolysis of cancer cells and FBiTE-mediated cytotoxicity toward FAP-expressing CAFs might be an effective strategy to overcome the barrier of the tumor-associated stroma, a key obstacle to oncolytic virotherapy." (PMID 34305902, 2021). "Fibroblast activation protein-α (FAP) is a transmembrane peptidase expressed on stromal cells and acts as a surrogate marker for cancer-associated fibroblasts (CAFs) which play a major role in the tumour microenvironment." (PMID 34525114, 2021). "Similarly, high FAP intensity was also associated with tumors showing high tumor grade and lymphovascular invasion (p < 0.05 and p = 0.03, respectively)." (PMID 32733792, 2020). "Taken together, the association of FAP expression on the mRNA and protein levels with multiple clinicopathological features known to be associated with poor prognosis supports our finding that FAP is also associated with tumor aggressiveness." (PMID 32733792, 2020). "Given that the transcriptomic analysis suggests that FAP may promote a protumorigenic environment, we investigated whether the localization of FAP in the tumor could be associated with its role in CRC invasion." (PMID 32733792, 2020). "The fibroblast activation protein (FAP) for example, is exclusively overexpressed on the stromal fibroblasts of healing wounds, rheumatoid arthritis and on 90% of tumor associated fibroblasts in a broad spectrum of epithelial cancers, making it a universal tumor marker." (PMID 32316521, 2020). "We found that tumor-associated pericytes marked by co-expression of fibroblast activation protein α (FAP) and PDGFRβ represent major stromal cell subsets in both human GBM and mouse GBM models, while a fraction of mesenchymal neoplastic cells also express FAP in patient tumors." (PMID 33308315, 2020). "(iv) Overexpression of certain enzymes such as, the fibroblast-activation protein-α (FAP-α) expressed by cancer-associated fibroblasts (CAFs) and matrix metalloproteinases (MMPs) secreted by tumor-associated inflammatory cells in the extracellular matrix." (PMID 32775317, 2020). "FAP is traditionally linked with tissue repair and extracellular matrix remodeling due to its dipeptidyl peptidase activity, however, it is one of the most upregulated genes in the tumor stroma and widely considered one of the most reliable CAF-markers." (PMID 33308315, 2020). "This property not only leads to increased drug accumulation in the tumor mass, but also avoids off targeting and associated side effects, which could rise hope on reduced myelotoxicity when targeting FAP by appropriate nano-vehicles." (PMID 30871158, 2019). "Several studies have implicated FAP in tumor growth and progression." (PMID 31527414, 2019). "Therefore, encoding a BiTE specific against FAP would ideally re-direct lymphocytes to become cytotoxic against the tumor stroma, improving virus spread in the tumor microenvironment." (PMID 30683154, 2019). "FAP is more widely associated with a population of CAFs in the tumour microenvironment." (PMID 30054470, 2018).
tumor (continued). "Furthermore, stromal expression of FAP is linked to immunosuppressive tumor microenvironment and poor prognosis in various cancers, suggesting a role in cancer progression and anti-tumor immunity." (PMID 28970566, 2017). "The association of FAP expression and a malignant tumor was well studied in a various tumor." (PMID 27936466, 2017). "In addition, two tumor-associated proteins FAP (fibroblast activation protein/seprase) and DPEP1 (dipeptidase 1) were absent from healthy and perilesional ECM." (PMID 26940881, 2016). "Furthermore, a FAP α antibody, FAP α vaccine, and modified vaccine all inhibit tumor growth and prolong survival in mouse models, suggesting FAP α is an adaptive tumor-associated antigen." (PMID 26985769, 2016). "Better preservation of vaccine-induced MAA-specific CD8+T cell response may also have been caused by the marked reduction of tumor-infiltrating ISCs after FAP+ stromal cell depletion." (PMID 26943036, 2016). "In addition, sensitivity analysis by tumor type indicated that an association between FAP overexpression and poor survival was evident for the three colorectal studies (HR: 1.72, 95% CI: 1.58–9.48, P = 0.009)." (PMID 25775399, 2015). "FAP has been shown on tumor-associated macrophages in human breast cancer." (PMID 26300881, 2015). "Consequently, FAPα is thought to be an adaptive tumor-associated antigen useful for tumor immunotherapy." (PMID 26305550, 2015). "A previous study demonstrated that FAP-expressing tumor-associated stromal fibroblasts contribute to suppression of immune responses in the tumor microenvironment and that ablation of this stromal population can elicit tumor killing by tumor antigen-specific T cells." (PMID 23554941, 2013). "For example, in transgenic mice, in which the diphtheria toxin receptor is expressed under the control of the FAP promoter, administration of diphtheria toxin, which only kills tumor-associated FAP-positive stromal cells, resulted in complete ablation of solid tumors." (PMID 24349329, 2013). "The bone marrow-derived tumor associated stromal components defined by FAP and FSP expression could be largely characterized as isolated cells, lacking organization near the periphery of the tumor." (PMID 22363446, 2012). "Hence, reduced FAP concentrations in cancer patients might reflect diminished release of FAP from tumor-associated fibroblasts or increased consumption of FAP within the tumor microenvironment." (PMID 40690098, 2025). "However, the association between FAP+ CAFs and TLSs in human tumor tissues is unclear." (PMID 41154405, 2025). "Additionally, FAP is associated with poor prognosis and the promotion of tumor growth." (PMID 40022239, 2025). "FAP is a type II transmembrane glycoprotein, with proteolytic activity rarely expressed in healthy adult tissue but overexpressed on the surface of cancer-associated fibroblasts of several tumor types, including the breast, esophagus, lung, pancreas, colon, and head and neck." (PMID 39140264, 2024). "Furthermore, analysis of the TCGA-LIHC database revealed that HCC patients with high Sema3C expression and the presence of FAP+ CAFs subset showed a significant association with advanced tumor stages/T stages compared to those with low Sema3C expression and FAP+ CAFs." (PMID 38956074, 2024). "However, the protease activity of FAP has been shown to be directly associated with tumor growth." (PMID 38540158, 2024). "Additionally, a high number of tumor-infiltrating lymphocytes (TILs) was observed via H&E staining, which may imply an association between FAP expression and tumor immunity." (PMID 39519118, 2024). "Hence, high intratumoral expression of 5-LO was closely associated with high FAP expression and may be associated with tumor malignancy in patients with IHCC." (PMID 38017374, 2023).
tumor (continued). "Fibroblast activation protein (FAP) is a type II membrane-bound glyocoprotein acting as serin protease of the dipeptidyl-peptidase family and can be detected on the cell surface of cancer-associated fibroblasts, which have been advocated to play a relevant tumor-promoting role." (PMID 35681588, 2022). "Furthermore, a lower density of YAP1 and FAPα is associated with an increased density of tumor-infiltrating CD8a+ T lymphocytes with a cytotoxic immune signature, implying that fibroblasts may also engage in recruiting regulatory leukocytes to the TME." (PMID 35986369, 2022). "Thus, FAP has been considered as a suitable target to eliminate tumor-associated fibroblasts." (PMID 34302116, 2022). "Researchers have identified distinct FAP/PDGFRβ dual-positive tumor-associated pericytes in the GBM microenvironment; these cells were demonstrated to be the major FAP-positive cells in GBM and might be CAF-like cells with tumorigenic roles in the GBM microenvironment." (PMID 34068501, 2021). "Thus, relative to directly targeting cancer cells, there may be diagnostic and treatment benefits associated with targeting the FAP+ tumor stroma." (PMID 34490078, 2021). "Malignant peritoneal ascites samples comprising cancer cells, tumor-associated macrophages (TAMs), CAFs, T cells—a majority of which displayed an exhausted phenotype—and soluble immunosuppressive factors were used as an ex vivo model system to investigate efficacy of EnAd-FAP-BiTE." (PMID 33863363, 2021). "Another study revealed that CAFs are closely associated with local angiogenesis while targeting FAP+ CAFs and administration of vascular disrupting agents that kill perivascular cells are associated with a less stable blood-tumor barrier and greater killing of tumor cells." (PMID 34490078, 2021). "However, the situation with tumour necrosis factor (TNF) produced by CAFs is more nuanced; the tumour-promoting immunosuppressive activity of FAP+ fibroblasts is associated with suppression of TNF signalling, yet TNF is also able to drive fibroblast activation in certain contexts." (PMID 31980749, 2020). "Additionally, our IHC analysis showed that the frequency of FAP-positive cells was associated with tumor budding score, a very well-known pathological marker associated with epithelial-to-mesenchymal transition and tumor invasion." (PMID 32733792, 2020). "One attractive stromal target is the fibroblast activation protein-α (FAP), a transmembrane serine protease that is highly expressed on the cell surface of cancer-associated fibroblasts (CAFs), which represent the key component in the tumor microenvironment of many cancers." (PMID 30683154, 2019). "Recently, it has been described as a novel class of monomeric tumor-targeted immunocytokines in which a single engineered IL-2 variant (IL-2v) with abolished CD25 binding is fused to the C-terminus of an antibody against the CEA or fibroblast activation protein-α (FAP)." (PMID 30619269, 2018). "Therefore, FAP α is considered to be an adaptive tumor-associated antigen for tumor immunotherapy." (PMID 26985769, 2016). "Therefore, we examined whether tumors resulting from hematogenous dissemination was also susceptible to immunotherapy using FAP-expressing tumor cells." (PMID 26394925, 2015). "Strategies to enhance tumor retention, such as multivalent FAP constructs and covalent binding approaches, are currently under investigation." (PMID 41510167, 2026). "Immunohistochemical reactivity against CD31 indicates that FAP is primarily expressed near irregular vascular spaces, the proposed area of tumor origin." (PMID 40694103, 2026). "An excellent correlation between uptake in 68Ga-FAPI-04 PET/CT and the tumoral FAP expression after immunohistochemical FAP-staining with a higher expression in the periphery and a lower amount in the tumor center was shown." (PMID 40694103, 2026). "CAFs create a barrier to prevent TILs from entering the tumor by secreting collagen, FAP, and chemokine." (PMID 41328341, 2026).
tumor (continued). "Fibroblast activation protein (FAP), known for its involvement in tumor invasion, matrix remodeling, and angiogenesis, has been implicated in various malignancies but has not been studied in JA so far." (PMID 40694103, 2026). "Immunohistochemical staining showed pronounced FAP expression in the excised tumor periphery, aligning with tracer-rich areas noted in the FAPI-PET." (PMID 40694103, 2026). "Although preclinical studies have demonstrated promising results across various tumour models using diverse radiolabelled FAP inhibitors, clinical translation remains limited by modest efficacy, short tumour retention, and highly heterogeneous responses." (PMID 41622307, 2026). "Clinical data showed that FAPα+ macrophages were enriched in the bone marrow versus peripheral blood of MM patients, and their abundance positively correlated with tumor burden." (PMID 41614659, 2026). "FAPI-46-based constructs retained nanomolar FAP affinity and enabled efficient enzyme-triggered payload release while maintaining selective tumor accumulation in vivo as visualized by 68Ga-PET." (PMID 41944234, 2026). "In PCa, stromal FAP is enriched in metastatic castration‐resistant tumours and correlates with disease progression." (PMID 41410015, 2026). "IHC confirmed strong, predominantly tumor cell-intrinsic FAP expression in MPNSTs, with minimal staining in neurofibromas and normal tissues." (PMID 41591566, 2026). "Further studies are warranted to validate its applicability in additional tumor entities and with other FAP-targeting ligands." (PMID 41714120, 2026). "Spatial transcriptomics revealed enrichment of FAP-high regions in MPNSTs and co-localization with tumor cell markers." (PMID 41591566, 2026). "In other tumor diseases, numerous FAP inhibitors have been investigated, and also theranostic approaches have been explored in nuclear medicine." (PMID 40694103, 2026). "Fibroblast activation protein (FAP) is overexpressed on the surface of cancer-associated fibroblasts of the tumor stroma and can be visualized by PET using radiolabeled FAP tracers." (PMID 41101974, 2026). "Before the advent of FAP PET imaging, detection of FAP in the tumor stroma of RCC by immunohistochemistry had been suggested for use as a biomarker for the presence of synchronous metastases and of metastases to the lymph nodes." (PMID 41101974, 2026). "Therapeutic evidence shows encouraging tumour retention and safety profiles for agents such as [177Lu]Lu-FAP-2286 and [90Y]Y-FAPI-46, while α-emitting radiotracers (e.g., [225Ac]Ac-FAPI-04) demonstrate potent antitumor effects in preclinical models." (PMID 41599688, 2026). "Multivariable Cox regression in MRI‐visible tumours, adjusted for age, GG, extra‐prostatic extension, and seminal vesicle invasion, confirmed stromal FAP (p = 0.041) and stromal αSMA (p = 0.042) as independent prognostic factors." (PMID 41410015, 2026). "Correlation analysis of clinicopathological parameters indicated that the proportion of FAP+ cells correlated with AJCC stage and tumor invasion depth; CPXM2+ cells correlated with tumor location; Epithelial CPXM2+ cells were associated with the patient's age." (PMID 42052481, 2026). "Collectively, our findings demonstrate that FAPα+ macrophages mediate MM immune evasion via dual mechanisms, positioning them as promising therapeutic targets to potentiate anti-tumor immunotherapies." (PMID 41614659, 2026). "Exemplarily, first‐generation FAP‐targeting agents showed limited tumor retention, with accumulation decreasing by 50% within 6 h post‐injection." (PMID 40888104, 2026). "Here, we identified fibroblast activation protein alpha (FAPα) as a highly attractive target for CAR-T cell therapy against GBM based on its dual expression pattern (on tumor cells and perivascular cells) in GBM." (PMID 41930329, 2026). "FAP tracers can be used for targeted radionuclide therapies, specifically destroying tumor cells while sparing healthy tissue." (PMID 40694103, 2026).
tumor (continued). "Fibroblast activation protein (FAP), a transmembrane serine protease overexpressed in tumor stroma, has emerged as a dual-purpose biomarker for cancer theranostics." (PMID 42006731, 2026). "Second‐generation FAP‐targeting agents demonstrate significantly improved tumor retention compared to first‐generation drugs (up to 8 d)." (PMID 40888104, 2026). "FAPI-PET/CT imaging accurately identified the tumor, with radiotracer uptake closely matching the distribution of FAP expression observed histologically." (PMID 40694103, 2026). "Spatial mapping revealed preferential enrichment of DSG2+CSCs at tumor margins, where they co-localized with FAP+myofibroblasts (myCAFs)." (PMID 41691490, 2026). "FAP is primarily expressed in the peripheral tumor tissue of JA, corroborated by studies showing its presence in human endothelial cells, where it influences microvascular reorganization and capillary morphogenesis through enzymatic activity." (PMID 40694103, 2026). "Functional studies investigating the role of FAP in tumor progression and signaling pathway interactions are therefore needed to deepen our understanding of FAPI-PET/CT diagnostics across different patient subgroups and to refine potential therapeutic targets." (PMID 40694103, 2026). "Fibroblast activation protein (FAP) has been proposed as a pan-tumor target for PET imaging using FAP-targeted tracers." (PMID 41101974, 2026). "We found that the expression of α-SMA, FAP and Vimentin were significantly elevated in the tumor tissues mixed with stromal cells." (PMID 40703348, 2025). "FAP plays an important role in the proliferation of cancerous cells through remodeling of the tumor micro-environment, intracellular signaling, immunosuppression and stimulating angiogenesis and tumor growth." (PMID 41463267, 2025). "Future research should focus on advancing imaging techniques that can accurately identify and monitor FAP expression dynamically within the tumour milieu." (PMID 40741380, 2025). "For example, FAP-2286 has demonstrated strong tumor uptake and retention in both preclinical models and early peptide-targeted radionuclide therapy trials, yet variable patient responses highlight the functional heterogeneity of CAF populations." (PMID 41441395, 2025). "Since FAP is a membrane protein specifically expressed by CAFs and is involved in nearly all tumor‐promoting processes, targeting FAP represents a promising approach to disrupt the protumorigenic functions of the tumor stroma." (PMID 40656546, 2025). "We detected cells that costained for FAP and markers of each subpopulation, confirming their presence in tumor tissue." (PMID 40215177, 2025). "The binding specificity of [89Zr]Zr-Nb159 to FAP was confirmed through a competitive binding inhibition in U87 tumor-bearing mice, as demonstrated by a ~ 55% reduction in tumor uptake by excess cold Nb159." (PMID 41460404, 2025). "Several studies have used FAP to target CAFs and demonstrated the feasibility of targeting CAFs together with early signs of reducing tumor burden." (PMID 40296919, 2025). "Payload-delivery strategies (e.g., antibody–drug conjugates to LRRC15/FAP) can leverage stromal–tumor co-expression but require the demonstration of tumor-dominant expression to mitigate off-tumor toxicity." (PMID 40940809, 2025). "In terms of enzyme activity inhibition, talabostat is one of the first small molecules to inhibit the dipeptidyl peptidase activity shared by DPPIV and FAP, showing a good anti-tumor effect." (PMID 40607439, 2025). "FAP expression on CAFs has been explored as a prognostic biomarker in several cancers, though its significance varies by tumor type." (PMID 41441395, 2025). "A competitive binding study confirmed its specificity to FAP on U87 tumors, as pre-injection with a tenfold molar excess of unlabeled Nb159 reduced tumor uptake by ~ 55% (3.78 ± 0.50 to 1.67 ± 0.26%ID/g)." (PMID 41460404, 2025).